IL1A (interleukin 1 alpha)
Diseases named in the same sentence as IL1A in open-access papers (continued):
Sharing a sentence is not in itself a finding about the gene and the disease.
Sepsis (continued). "Using an in vivo LPS-induced sepsis model, we measured decreased serum levels of IL-1β, IL-1α, and IL-6 as well as increased survival of mice treated with ML133 or in Lyz2-cre-Kcnj2f/f mice compared to controls." (PMID 35729093, 2022). "The elevated IL-1α levels in our study were consistent with a recent murine study that also showed increased IL-1α during polymicrobial sepsis." (PMID 32479514, 2020). "The results obtained showed that the rats in the untreated sepsis group showed significantly elevated levels of pro-inflammatory cytokines (IL-1α, IL-2, TNF-α, IL-6, IFN-γ, IL-1β) in plasma." (PMID 32076015, 2020). "Five cytokines exhibited a significant sex × sepsis × age interaction [G-CSF (p = 0.005), IL-17 (p = 0.023), IL-1α (p = 0.038), KC (p = 0.044), MCP-1 (p = 0.0239)]." (PMID 31278440, 2019). "Thrombin-cleaved IL-1α was detected in humans during sepsis, pointing to the relevance of this pathway for normal physiology and the pathogenesis of inflammatory and thrombotic diseases." (PMID 30926232, 2019). "It has long been established that IL-1α is an early mediator of fever and an early signaling molecule in sepsis." (PMID 31727174, 2019). "Neutrophils and monocytes from adults with sepsis have reduced activation and production of pro inflammatory cytokines (IL-1α, IL-6, TNF-α) in response to LPS." (PMID 31612119, 2019). "The secretion of proinflammatory cytokines, such as TNF-α and IL-1 (including IL-1α and IL-1β), in sepsis has been demonstrated in numerous studies." (PMID 31333903, 2019). "For example, the administration of miR-146a was found to reduce proinflammatory cytokines (TNF-α, IL-1β, and IL-1α) and inflammatory edema in an LPS-induced model of sepsis in rats by targeting the TLR-4/NFκB pathway." (PMID 31671621, 2019). "Lastly, cleaved IL-1α level was lower during experimental endotoxemia in IL-1α TM mice, implying generation of p18 IL-1α during human sepsis and mouse endotoxemia." (PMID 30926232, 2019). "CGA-JK3 consequently interrupted IKKβ-inducible NF-κB activation and NF-κB-regulated expression of TNF-α, IL-1α or HMGB-1 gene, thereby improving TLRs-associated redundant inflammatory responses in endotoxemia, polymicrobial sepsis and ALF." (PMID 28145460, 2017). "Similar to the serum results, the concentration of IL-6, TNF-α, IL-1β and IL-1α in the colonic wall rose significantly following CLP-induced sepsis." (PMID 27044016, 2016). "On univariate logistic regression analysis, the distribution of genotypes at positions IL-1α (−889 C/T), IL-4 (−1098 T/G), IL-10 (−1082 A/G), allele A of TNF-α (−238) and allele T of IL-10 (−889) were significantly (p < 0.05) predominant in sepsis." (PMID 26561011, 2015). "IL-1α was higher in the serum of sepsis (5.4 ± 2.8 vs. 18.6 ± 7.8 pg/ml, HC vs. sepsis, p < 0.05) than non-sepsis (5.4 ± 2.8 vs. 7.2 ± 2.6 pg/ml, HC vs. non-sepsis)." (PMID 26561011, 2015). "Genome-wide linkage studies in mice identified a correlation between IL-1α levels and mortality during GAS sepsis, suggestive that IL-1α contributes to cytokine storm during sepsis." (PMID 26500655, 2015). "Within the human body, IL-1α mediates normal physiological functions ranging from induction of vascular permeability and fever during sepsis to increased secretion of additional cytokines in autoimmune diseases." (PMID 25237386, 2014). "The results demonstrated that the IL-1A-889C/T, IL-1B-3594C/T, and IL-1RN VNTR polymorphisms had significant associations with the risk of sepsis, although some results were limited by the small number of studies." (PMID 24428862, 2014). "Interleukin-1 (IL-1) family is a critical mediator of immune response to sepsis with two agonists (IL-1α and IL-1β) and one antagonist (IL-1 receptor antagonist: IL-1ra)." (PMID 24428862, 2014).
Sepsis (continued). "Further, neuroimmunopathogenesis of sepsis involves peripheral release of proinflammatory cytokines (TNF-α, IL-1α, IL-1β, and IL-6) increasing blood brain barrier (BBB) permeability, generating neuroinflammation and sepsis associated sickness behaviour." (PMID 25018890, 2014). "TNF-α and IL-1 (a term used for a family of proteins, including IL-1α and IL-1β) are among the most extensively studied cytokines in sepsis pathophysiology." (PMID 23853427, 2013). "In contrast, injection of human recombinant IL-1α protects against experimental sepsis in a time-dependent manner." (PMID 23675299, 2013). "Key pro- and anti- inflammatory mediators like IL-1α, MIP-1β, RANTES, CXCL-1, IL-6 and IL-10, implicated to play a role in sepsis were up-regulated at both the early and late time points." (PMID 23009705, 2012). "We observed that metalloproteinases and sE-selectin play a role in the distinction between SIRS and sepsis, and that IL-1α, IP-10, sTNF-R2 and sFas appear to be indicative for the progression from sepsis to septic shock." (PMID 20165718, 2010). "We found that in vivo neutralization of endogenous MCP-1 during acute sepsis led to substantial decreases in the transcript levels for IL-1α, IL-1β, and IL-6, as well as MCP-1 itself, in the diaphragm." (PMID 20950459, 2010). "While interleukin 1 receptor 2 (IL1R2) acts as a decoy receptor for IL1α/β, its potential impact on cell metabolism and death during sepsis remains unclear." (PMID 40704655, 2025). "Thus, IL-1α has become an important drug target in many diseases such as sepsis, chronic toxoplasma infection, inflammatory bowel disease, Crohn’s disease, and diabetes mellitus." (PMID 37007020, 2023). "However, increased IL-1α in plasma or serum of infants with either late-onset sepsis, neonatal sepsis or meningitis shows promise as a predictive biomarker for neonatal sepsis." (PMID 36769133, 2023). "Interestingly, anakinra (blocking both IL-1α and IL-1β) has shown promises in treating these patients with hyperinflammatory disorders, sepsis with multiorgan failures." (PMID 35431536, 2022). "GzmB is able to enhance the proinflammatory activity of IL-1α by proteolytic cleavage, although GzmB deficiency does not protect from sepsis." (PMID 32655547, 2020). "Our meta-analysis indicated that IL-1A-889, IL-1B + 3954 and IL-1RN VNTR might be associated with sepsis susceptibility." (PMID 24428862, 2014). "These were IL-1α related to apoptosis and inflammation, IP-10 related to leukocyte recruitment into inflamed organs and sTNF-R2 and sFas related to a pro-inflammatory environment with little beneficial effect on functional modulation of the sepsis scenario." (PMID 20165718, 2010). "These were IL-1α related to apoptosis and inflammation, IP-10 related to leukocyte recruitment into inflamed organs, sTNF-R2 and sFas related to a pro-inflammatory environment with little effect on a beneficial functional modulation of the sepsis scenario." (PMID 20165718, 2010). "From these proteins, TNFα, IL-1α, Lck, NOS2, SOD2 and CD36 were selected for validation by Western blot on murine bone marrow-derived macrophages due to their relevant roles in the NF-κB, iNOS, oxidative stress, and phagosome signaling pathways, which are closely associated with sepsis pathogenesis." (PMID 40725160, 2025). "Reduced expression levels of TNF-α, IL-1α, and C1qA were exhibited in the hippocampus of the berberine treatment group, and attenuated effect of declining neo-neuron, activation of microglia and astrocytes in the hippocampus of mice with sepsis were also found." (PMID 34867376, 2021). "Moreover, the treatment with DIDS did not reverse the number of Iba-1-, CD86- and iNOS-positive cells, nor affected microglia branching, although previous studies demonstrated that DIDS can inhibit the expression and secretion of serum IL1-α and macrophage activation in a sepsis animal model." (PMID 31575916, 2019).
Sepsis (continued). "Sequence-specific primer based PCR indicated that eight polymorphic loci IL-1α /-889, IL-1β/-511, IL-1R (pstI 1970), TGF-β/ code 10, TNF-α/-308, TNF-α/-238, IL-6/+565 and IL-10/-1082, out of 22 SNPs are significantly associated with sepsis morbidity and outcome." (PMID 26561011, 2015). "In sepsis, the severe systemic inflammatory response, known as cytokine storm, involves the excessive release of inflammatory cytokines such as TNF-α and IL-1α into the bloodstream." (PMID 40725160, 2025). "Furthermore, the baseline excessive pro-inflammatory cytokines, such as TNF-α, IL-6, IL-1α, IL-1β, and IL-18, released after hepatic cell damage in NASH or further stage, might predispose NAFLD patients to cytokine storm in the setting of sepsis, resulting in worse outcomes." (PMID 39407795, 2024). "Inhibition of Caspase-11 activation leads to less IL-1α and HMGB1 release in the peritoneal cavity, and it reduces abdominal inflammation during sepsis." (PMID 33055424, 2020). "Elevated levels of IL-1α, TNF-α and IL-10 were observed in patients with sepsis compared to healthy controls and non-sepsis patients." (PMID 26561011, 2015). "The up-regulation of TNF-α, IL-1α, IL-1β, CXCL-10, SOCS3, IL-10 at 1 and 2 h in the present study was similar to that observed in blood profiles of sepsis patients at early stages." (PMID 23009705, 2012). "Early sepsis disease 12 h post-infection was characterized by cytokine storm, with concentrations of IFN-γ, CCL2, IL-6, IL-17A, IL-1α, IL-10 and M-CSF significantly elevated in multiple tissues up to 7 days post-infection when mice had recovered from objective clinical measures of disease." (PMID 41910926, 2026). "Berberine-mediated blockade of HMGB1/receptor for advanced glycation end products signaling reduces the expression of TNF-α, IL-1α, and complement C1q A chain in the hippocampus of CLP mice, inhibits the activation of microglia, and thus alleviates sepsis-induced cognitive impairment." (PMID 38734709, 2024). "Some studies have shown that the levels of characteristic cytokines such as TNF‐α, IL‐6, IL‐1β, IL‐1α, IL‐12, IL‐17, CXCL1, CXCL2, MCP‐1, IL‐8, CXCL10, GM‐CSF, M‐CSF, and G‐CSF in patients with septicemia are significantly higher than those in normal volunteers." (PMID 36684101, 2023). "Mean cytokine level of IL1A, IL12, IL21, IL23 was increased in survivors of sepsis." (PMID 33667236, 2021). "Using CLP, a clinically relevant murine model of gram-negative polymicrobial sepsis, we observed that FeTPPS treatment markedly inhibited caspase-11-dependent release of IL-1α and IL-1β, but did not affect the secretion of TNF or IL-6." (PMID 33854044, 2021). "Both male and female mice treated with either anti-IL-1α or anti-IL-1β alone as well as controls treated with unreactive IgG did not develop abscesses or sepsis." (PMID 28358036, 2017). "Both IL-1α and IL-1Ra are differentially expressed in survivors and nonsurvivors among children with sepsis and IPD, respectively." (PMID 27170644, 2016). "For example, interleukin 1 alpha (IL1α), responsible for the production of inflammation, as well as the promotion of fever and sepsis, was not expressed in the EPC and CHO-K1 cells." (PMID 25344771, 2014). "Examination of sera from ARDS and age-matched control individuals revealed no p18 in control individuals, but p18 generation in sepsis-associated ARDS, with all patient sera that contained p18 IL-1α also positive for microbiology in bronchoalveolar lavage fluid." (PMID 30926232, 2019). "However,TNF-α -238(AA), IL-1α-889(CC) and IL-10-1082(GG) genotypes appeared to be a higher producer by CBA assay, but IL-10 masked the expression of the high producing genotype of TNFα -238(AA) in sepsis patients." (PMID 26561011, 2015).
Sepsis (continued). "When incubated for 6 hours without extrinsic stimuli, whole blood from sepsis patients, which already contained greater inflammatory cytokine concentrations than that of healthy volunteers, showed a significant further increase of supernatant TNF, IL-6, IL-8, IL-1α, and IL-1β concentrations." (PMID 37869001, 2023).
colitis (77 papers, 2008 to 2026). Inflammation of the colon. "Consistent with findings in colitis, IL-1α-deficient mice in the AOM/DSS-induced model experienced less weight loss and had lower pathological scores compared to WT mice." (PMID 40767963, 2025). "Regarding pro-inflammatory cytokines, colitis caused a significant increase of IL-1α and IL-1β in both Mcpt-4fl/fl and Mcpt-4ΔCre mice, with Mcpt-4 deficiency promoting higher production of IL-1α and IL-1β." (PMID 40697820, 2025). "Our investigation corroborates earlier work showing that IL-33 facilitates the generation of IgA, contributing to the preservation of gut microbial homeostasis while mitigating IL-1α–induced colitis and colitis-associated cancer." (PMID 40048372, 2025). "Next, we seek to interpret the functions of those DA microbes using MSEA to shed light on the mechanism of colitis-resistance for the IL-1α-deficient mice." (PMID 33293650, 2020). "Specifically, we show that the mild colitis symptoms seen in IL-1α-deficient mice following administration of DSS are correlated with the unique gut microbiota compositions of the mice." (PMID 29766049, 2018). "In a subsequent study, the role of IL-1α as a driver of DSS-induced colitis in IL-33-deficient mice has also been established." (PMID 29766049, 2018). "Nevertheless, more research is needed to prove causation and exact interactions between cell-associated IL-1α, microbes, and cellular/cytokine pathways in the pathogenesis of colitis." (PMID 29766049, 2018). "Overall, it appears that the deficiency of IL-1α leads to a more moderate form of colitis; however, exposure to WT microbiota exacerbates disease in this group of mice." (PMID 29766049, 2018). "In previous studies, we showed that IL-1α deficiency moderates DSS-induced colitis with minimal inflammation and complete healing." (PMID 29766049, 2018). "Moreover, IL-1α-deficient mice significantly suppressed tumor growth in the context of IL-33 deletion-induced colitis, highlighting IL-1α’s crucial role in promoting colitis and tumor development." (PMID 40767963, 2025). "On the other hand, the pathogenic transformation of CD4+ T cells into GM-CSF-producing T cells in vivo, triggered by antigen presentation by tissue macrophages and the production of IL1α and IL1β associated with the inflammasome, facilitates the promotion of colitis and CAC." (PMID 38892354, 2024). "In the spontaneous TCRα‐deficient model of colitis, an increase in IL1A and IL1B occurs in young mice (age 4–8 weeks), suggesting that the lack of TCR receptor will consequently lead to an increase in the expression of these cytokines even before there is histological evidence of colitis." (PMID 38992956, 2024). "In this study, we tested whether the protective effects of IL-1α deficiency on DSS-induced colitis correlate with changes in the gut microbiota and whether manipulation of the microbiota by cohousing can alter patterns of colon inflammation." (PMID 29766049, 2018). "In this study, we investigated whether the protective effects of IL-1α deficiency on DSS-induced colitis correlate with changes in the gut microbiota and whether manipulation of bacterial populations by cohousing can alter disease progression." (PMID 29766049, 2018). "Our goal in this study was to determine whether the protective effects of IL-1α deficiency on DSS-induced colitis correlate with changes in the gut microbiota and whether cohousing can modulate disease outcomes." (PMID 29766049, 2018). "Moreover, high levels of A. muciniphila were reported in IL-33-deficient mice and correlated with elevated expression of IL-1α, which was essential for induction of a severe form of colitis." (PMID 29766049, 2018). "DSS colitis resulted in elevated levels IL‐6, IL‐1a, TNF‐ɑ, and MCP‐1 in the colons of PBS control‐treated mice compared to naïve mice." (PMID 39815783, 2025).
colitis (continued). "IL-1α plays a dominant role in the pathogenesis of DSS-induced acute colitis, and intestinal epithelium-specific knockout of IL-1α significantly improved the symptoms of colitis, underscoring the critical proinflammatory role of epithelium-derived IL-1α." (PMID 40767963, 2025). "Blocking IL-1α with FLO1 mAb (a murine-specific monoclonal antibody) markedly reduced ileitis/colitis severity, while paradoxically elevating IL-18 (a gut barrier integrity promoter) and inflammatory markers." (PMID 40661957, 2025). "For instance, LD IL-10 and anti-IL1-α antibodies demonstrate promise in colitis and osteoarthritis models, while a combination of IL-4, IL-10, and anti-IL1-α antibodies outperforms DMARDs in rheumatoid arthritis." (PMID 38792574, 2024). "Accordingly, IL-33-deficient mice developed a dysregulated gut microbiota, and altered gut microbiota in IL-1α-knockout mice resulted in protection against DSS-induced colitis." (PMID 36339623, 2022). "Blockade of IL-1α with a neutralizing antibody protects mice from acute DSS-induced colitis and modifies the gut microbiota into an anti-inflammatory flora." (PMID 35693797, 2022). "Mice deficient in Il1a were more resistant to DSS colitis, whereas Il1b−/− mice had more severe colitis and impaired tissue repair capacity compared to wild-type (WT) mice." (PMID 33562334, 2021). "A recent study revealed that the resistance of Il1a−/− to DSS colitis is microbiota dependent since co-housing of these mice with WT controls diminished their disease resistance." (PMID 33562334, 2021). "ELISA data showed that the expression levels of TNF-α, IL-1α, IL-6, and IL-8 in colitis mice were significantly reduced compared with those in control samples." (PMID 34456974, 2021). "In this stage of colitis, food intake with βGh (CβGh+ group) up-regulated the expression of the Il13, Il21, Il27, and Lta genes and down-regulated the expression of the Il1a, Il11, and Il17a genes." (PMID 33923129, 2021). "In a colitis model, the authors demonstrated that the loss of the ODC gene leads to pronounced induction of inflammatory cytokines including GM-CSF, TNF-α, IL-1α and IL-1β, and IFN-γ as well increased macrophage polarization towards M1." (PMID 34206987, 2021). "Elevated cytokines in stool were previously detected in the context of gut inflammation, while in a murine model of colitis IL-1α secreted by intestinal epithelium was the main driver of immune activation." (PMID 33117362, 2020). "In the TNBS mouse model of colitis, berberine reduces IFNγ, IL-1α, IL-6, IL-17, and TNFα expression in colonic tissues and sera and suppresses Th1 and Th17 cells through reduction of STAT1, STAT3, and NF-κB phosphorylation." (PMID 32855621, 2020). "IL-1α in its precursor form, released from damaged IECs following onset of colitis, acts as a classical alarmin by initiating local inflammation." (PMID 31231388, 2019). "In correlation with the microbiota changes, cohousing also exacerbated other parameters of colitis in IL-1α KO mice as seen by DAI, survival, and histological scores." (PMID 29766049, 2018). "We demonstrate here that IL-1α has a clear influence on the gut microbiota composition, as well as on the severity of colitis." (PMID 29766049, 2018). "In colitis groups, n-3 diet upregulated IL-1A, TLR-2, and MA2K3 genes while n-9 diet upregulated TLR-4 genes (P = 0.044, P = 0.013, and P = 0.021, resp.)." (PMID 29670469, 2018). "Accordingly, separately raised WT mice manifested a severe form of DSS-induced colitis, whereas IL-1α KO mice displayed a more resistant phenotype." (PMID 29766049, 2018). "IL-1α release by necrotic intestinal epithelial cells in a murine model of chemically induced colitis induced cytokine production by mesenchymal cells and reactivated colon inflammation post-recovery when delivered via enema." (PMID 29922293, 2018).